CHST11 (carbohydrate sulfotransferase 11)
Description:
Catalyzes the transfer of sulfate to position 4 of the N-acetylgalactosamine (GalNAc) residue of chondroitin. Chondroitin sulfate constitutes the predominant proteoglycan present in cartilage and is distributed on the surfaces of many cells and extracellular matrices. Can also sulfate Gal residues in desulfated dermatan sulfate. Preferentially sulfates in GlcA->GalNAc unit than in IdoA->GalNAc unit. Does not form 4, 6-di-O-sulfated GalNAc when chondroitin sulfate C is used as an acceptor.
Synonyms: C4ST-1; C4ST1; C4ST; HSA269537; OCBMD
Tractability: Antibody: UniProt predicts a signal peptide or a membrane-spanning region. PROTAC: ubiquitination databases record sites on it.
Gene: Protein-coding gene on chromosome 12 (104,455,295 to 104,762,014, forward strand). Ensembl gene ENSG00000171310.
Subcellular location: Golgi apparatus membrane
Subcellular location (Human Protein Atlas): Golgi apparatus
Pathways (Reactome):
Metabolism: CS-GAG biosynthesis
Gene Ontology:
Molecular function: chondroitin 4-sulfotransferase activity; dermatan 4-sulfotransferase activity; sulfotransferase activity; N-acetylgalactosamine 4-sulfate 6-O-sulfotransferase activity
Biological process: chondroitin sulfate proteoglycan biosynthetic process; proteoglycan biosynthetic process; carbohydrate biosynthetic process; glycoprotein biosynthetic process
Cellular component: membrane; Golgi membrane; Golgi apparatus
Genetic constraint (gnomAD): Loss-of-function variants: 9 observed, 30.76 expected, observed/expected ratio (o/e) 0.29, 90% interval 0.17 to 0.51. The synonymous counts are far from expectation, so gnomAD's model fits this gene poorly and the ratio says little. Missense variants: 342 observed, 473.55 expected, observed/expected ratio (o/e) 0.72, 90% interval 0.66 to 0.79. Synonymous variants: 150 observed, 197.76 expected, observed/expected ratio (o/e) 0.76, 90% interval 0.66 to 0.87.
Homologues: Orthologues: chimpanzee CHST11 (100% identical), macaque CHST11 (100% identical), dog CHST11 (97% identical), mouse Chst11 (97% identical), pig CHST11 (97% identical), tropical clawed frog chst11 (90% identical), rat Chst11 (88% identical), guinea pig CHST11 (86% identical), zebrafish chst11 (79% identical). Paralogues in human: CHST13 (46% identical), CHST12 (37% identical), CHST8 (36% identical), CHST9 (33% identical), CHST14 (32% identical), CHST10 (29% identical).
Diseases named in the same sentence as CHST11 in open-access papers:
CHST11 is named in the same sentence as 69 diseases in open-access papers, as found by Europe PMC text mining. Sharing a sentence is not in itself a finding about the gene and the disease. The quoted sentences say what the papers report.
breast carcinoma (15 papers, 2011 to 2024). "For example, the overexpression of carbohydrate sulfotransferase 11 (CHST11) in breast cancers was associated with poor survival." (PMID 36880364, 2023). "An association between CHST11 expression and distant metastasis in breast cancer patients has been reported." (PMID 25586191, 2015). "Publicly available datasets were used to examine the association of CHST11 expression to aggressiveness and progression of breast cancer." (PMID 25586191, 2015). "Limited studies have indicated that CHST11 expression is enhanced in aggressive breast cancers, multiple myeloma, and ovarian cancer." (PMID 37076815, 2023). "Quantitative real-time RT-PCR was employed to confirm the expression profile of CHST11 in breast cancer cell lines." (PMID 25586191, 2015). "Our current data suggest that the expression levels of CHST11 can predict progression of breast cancer and more aggressive phenotypes." (PMID 25586191, 2015). "Given the role of CS and the significance of CHST11 expression in tumor growth and metastasis, these findings have significant implications for the development of novel prognostic strategies in breast cancer." (PMID 25586191, 2015). "We have demonstrated that the expression levels of CHST11 correlate with the expression of P-selectin-reactive surface CS and aggressiveness of human breast cancer cells." (PMID 25586191, 2015). "Our previously published data analyzing CHST11 expression in a set of commonly used human breast cancer cell lines suggest that CHST11 expression is low in luminal and high in basal-like cell lines." (PMID 25586191, 2015). "We have shown that a particular sulfation pattern mediated by the expression of carbohydrate (chondroitin 4) sulfotransferase-11 (CHST11) correlates with P-selectin binding and aggressiveness of human breast cancer cell lines." (PMID 25586191, 2015). "The comparison showed average increases of 2–3.6-fold in CHST11 expression in breast cancer compared to normal tissue." (PMID 25586191, 2015). "The data from several studies were analyzed to compare CHST11 expression in breast carcinoma versus normal breast tissue." (PMID 25586191, 2015). "In another study on breast cancer cell lines using genome wide methylation profiling, the authors reported that CHST11 is hypermethylated in ER-positive and hypomethylated in ER-negative cell lines." (PMID 25586191, 2015). "We have shown that the expression of CHST11 is elevated in tumor cells compared to normal cells of breast cancer patient tissue specimens." (PMID 25586191, 2015). "Because of its potential role in breast cancer metastasis, determining mechanisms controlling CHST11 expression is of great interest." (PMID 25586191, 2015). "Consistent with our data, CHST11 expression has been shown to be greater in human breast carcinoma compared to normal breast tissue and in malignant plasma cells from myeloma patients compared to normal bone-marrow plasma cells." (PMID 21658254, 2011). "In order to establish a translational relevance, we examined the expression of CSPG4 and CHST11 in specimens from breast cancer patients to compare the level of expression of these genes between normal and malignant tissues." (PMID 21658254, 2011). "The CHST11 gene was highly expressed in aggressive breast cancer cells but significantly less so in less aggressive breast cancer cell lines." (PMID 21658254, 2011). "Previously, C4ST-1 (Gene symbol: CHST11) was shown to be upregulated in breast cancer cells." (PMID 34113616, 2021). "CHST11 might play a direct role in progression of breast cancer and that its expression was controlled by DNA methylation." (PMID 28968955, 2017). "We have shown that the expression of CHST11 is upregulated in tumor tissues of breast cancer patients compared to their normal tissues and that the expression levels of the gene in breast cancer cell lines correlate with CS-A expression, P-selectin binding and aggressive phenotype." (PMID 25586191, 2015).
breast carcinoma (continued). "Our investigation of the methylation status of CHST11 in breast cancer cells clearly demonstrates an association between lack of expression of this gene and hypermethylation of a CpG island of its DNA." (PMID 25586191, 2015). "Our data strongly suggest that the expression of CHST11 and its role in defining metastatic potential of tumor cells should be seriously considered when demethylating agents are used for medical treatment of breast cancer patients." (PMID 25586191, 2015). "To determine whether the same CpG island can be methylated differently in actual breast cancer, we examined the methylation status of the CpG island of CHST11 gene in 5 de-identified clinical breast cancer specimens." (PMID 25586191, 2015). "The expression of such genes, including CHST11, may be activated by the clinical use of hypomethylating agents and this may promote more aggressive forms of breast cancer." (PMID 25586191, 2015). "The present study was performed to evaluate the prognostic value of CHST11 expression and determine whether aberrant DNA methylation controls CHST11 expression in breast cancer." (PMID 25586191, 2015). "Transient transfection of the human breast cancer cell line MDA-MB-231 with the siRNAs for carbohydrate (chondroitin 4) sulfotransferase-11 (CHST11) and chondroitin sulfate proteoglycan 4 (CSPG4 ) was used to investigate the involvement of these genes in expression of surface P-selectin ligands." (PMID 21658254, 2011). "Moreover, the expression of CHST11 has been correlated with breast-cancer progression." (PMID 35712490, 2022). "Therefore, variation in the expression of CHST11 in breast cancer cells may be controlled by DNA methylation." (PMID 25586191, 2015). "Therefore, methylation status of CHST11 CpG might be a useful marker to differentiate between luminal and basal-like breast cancer subtypes, however, a larger sample size is required to confirm this." (PMID 25586191, 2015). "To examine whether DNA methylation controls variation and regulation of CHST11 in breast cancer cell lines, we examined DNA methylation of the CHST11 sequence in a section of its CpG island covering part of its promoter, its first exon, and a portion of its first intron." (PMID 25586191, 2015). "Of these sulfotransferases, it has been reported that the expression of CHST11 and CHST15 is upregulated in breast cancer cells." (PMID 35712490, 2022). "As mentioned in Introduction, CS is modified by sulfation by multiple sulfotransferases, including CHST11 and CHST15, which are involved in the synthesis of E units and are upregulated in breast cancer cells." (PMID 35712490, 2022). "CHST11 gene that specifically mediates 4-O sulfation of CS is highly expressed in MDA-MB-231 breast cancer cells and breast cancer tissues." (PMID 24455486, 2014). "CHST11 gene that specifically mediates 4-O sulfation of CS was highly expressed in MDA-MB-231 breast cancer cells and breast cancer tissues." (PMID 24205138, 2013). "We further showed that the expression of CHST11 and CSPG4 is elevated in tumor tissues from breast cancer patients." (PMID 21658254, 2011). "Considering a wild-type situation, which can mimic the tumor microenvironment of human patients, several reports have shown a direct link between the expression of CHST11 (involved in decorating CSPG4 with chondroitin-4-sulfate) and the increased metastatic potential of breast cancer cells." (PMID 31949431, 2019).
ovarian carcinoma (10 papers, 2018 to 2025). A malignant neoplasm originating from the surface ovarian epithelium. "Western blot analysis of tissue homogenates showed high CHST11 expression, which was individually associated with shorter progression-free survival in ovarian cancer (N = 216, P = 0.027)." (PMID 37545696, 2023). "The observed increase in CS-4S and decrease in CS-0S disaccharides in ovarian cancer patients, likely due to elevated CHST11 activity, corresponds with prior research demonstrating increased CS disulfation in ovarian cancer tissues." (PMID 39583112, 2024). "CHST11 is an independent prognostic factor for ovarian cancer, and chondroitin sulfate is overexpressed in the ovarian cancer extracellular matrix." (PMID 32785160, 2020). "Carbohydrate sulfotransferases (CHSTs) are overexpressed in ovarian cancer patients, including CHST11, CHST12, CHST13, and CHST15." (PMID 32785160, 2020). "Increased tissue expressions of CHST11, CHST12 and CHST15 were shown to be unfavourable prognostic factors of ovarian cancer, GBM and pancreatic cancer, respectively." (PMID 37545696, 2023). "The same was observed previously for the chondroitin sulfate sulfotransferases CHST11 and CHST15 in ovarian cancer patients." (PMID 34201657, 2021). "Mutations of CHST3 gene cause skeletal dysplasia, chondrodysplasia, and autosomal recessive multiple joint dislocations while increased tissue expression of CHST11, CHST12 and CHST15 is an unfavourable prognostic factor in ovarian cancer, glioblastoma and pancreatic cancer, respectively." (PMID 37545696, 2023). "Carbohydrate sulfotransferase CHST11 was shown to be elevated in ovarian cancer patients in tumor tissues irrespective of the histological subtype, FIGO stage or post-operative residual tumors." (PMID 34201657, 2021). "Expressions of Chondroitin-4-sulfotransferase (CHST11) as well as other CHSTs in ovarian cancer samples are significantly higher than that in non-malignant ones, indicating poor prognosis." (PMID 31655797, 2019).
chondrodysplasia (8 papers, 2012 to 2023). "Given that CHST11 deficiency causes severe chondrodysplasia in mice that is similar to human limb malformation, these results underscore the importance of chondroitin modification in normal skeletal development." (PMID 26436107, 2015). "Interestingly, mice homozygous for a loss-of-function mutation in the CHST11 gene die shortly after birth and exhibit severe chondrodysplasia." (PMID 36727109, 2023). "Mice lacking functional Chst11 (C4ST-1) develop chondrodysplasia while mice deficient of functional Chst15 (GalNac4S-6ST) lack GalNAc 4,6 disulfate residues but develop no apparent abnormalities." (PMID 25793894, 2015).
colorectal cancer (5 papers, 2020 to 2023). A primary or metastatic malignant neoplasm that affects the colon or rectum. "Contrarily, other studies have reported that expression of C4-S sulfotransferases including CHST11 seems to be downregulated in colorectal cancers." (PMID 32231047, 2020). "However, other research revealed that CHST11 expression was decreased with increasing colorectal cancer stage, and expression of CHST11 diminished in hepatocellular carcinoma correlated positively with malignancy." (PMID 37076815, 2023). "Also, high expression of the CHST11 predicts poor disease-free survival of lung, breast and colorectal cancer patients." (PMID 32231047, 2020). "However, the role of CHST11 in the occurrence and development of colorectal cancer is not yet clear." (PMID 34294834, 2021).
Costello syndrome (4 papers, 2015 to 2025). Costello syndrome (CS) is a rare multisystemic disorder characterized by failure to thrive, short stature, developmental delay or intellectual disability, joint laxity, soft skin, and distinctive facial features. "Suppression of oncogenic HRAS signaling in Costello syndrome fibroblasts increases CHST11 expression." (PMID 37076815, 2023).
lung carcinoma (4 papers, 2021 to 2024). "The elevated expression of CHST11 in patients with lung cancer and pancreatic cancer is correlated with poor prognosis." (PMID 38565604, 2024). "Previous research has suggested that Chst11 promotes lung cancer metastasis via the changing intracellular iron metabolism." (PMID 39273313, 2024). "This includes genes involved in cancer progression such as Kif26a, Acer2, Serpine1, Nr1d2, Efnb2 as well as Chst11, which have all previously been shown to be deregulated in various forms of cancer, including lung cancer." (PMID 39273313, 2024). "Interestingly, elevated CHST11 expression, the enzyme required for CSA 4-O-sulfation, is also associated with poor DFS in three independent lung cancer cohorts." (PMID 34503301, 2021). "Therefore, the epigenetic deregulation and differential expression of Chst11 may play a role in the initiation of smoking-induced lung cancer." (PMID 39273313, 2024). "For example, the high expression of CHST11, the enzyme specifically required for CSA 4-O-sulfation, was significantly correlated with poor relapse-free survival in three independent lung cancer cohorts." (PMID 34966741, 2021).
glioma (3 papers, 2020 to 2023). A benign or malignant brain and spinal cord tumor that arises from glial cells (astrocytes, oligodendrocytes, ependymal cells). "Inhibition of CHST11 and CHST3 could potentially suppress the proliferation of glioma cell via the PI3K/AKT pathway." (PMID 34288811, 2021). "Furthermore, CHST11 and CHST13 have been reported as oncogenes in gliomas." (PMID 34288811, 2021).
hepatocellular carcinoma (3 papers, 2021 to 2023). A malignant tumor that arises from hepatocytes. "For example, the expressions of CHST11 and CHST13 increased in human hepatocellular carcinoma tissues than in adjacent tissues and promoted metastasis and drug resistance by activating the MAPK pathway." (PMID 34288811, 2021).
myeloma (3 papers, 2011 to 2023). "Therefore, further studies are required to understand whether modulating the anionic charge density on the CS chains of serglycin by silencing CHST11 expression myeloma cells may be an alternative approach to target myeloma exosomes." (PMID 29088739, 2017). "Interestingly, gene array analysis found that the expression of CHST11 (also known as C4ST1), a sulfotransferase gene responsible for the 4-O-sulfation of CS chains, is highly upregulated in myeloma patients compared to healthy donors." (PMID 29088739, 2017).